QTRT2 (queuine tRNA-ribosyltransferase accessory subunit 2)
Description:
Non-catalytic subunit of the queuine tRNA-ribosyltransferase (TGT) that catalyzes the base-exchange of a guanine (G) residue with queuine (Q) at position 34 (anticodon wobble position) in tRNAs with GU(N) anticodons (tRNA-Asp, -Asn, -His and -Tyr), resulting in the hypermodified nucleoside queuosine (7-(((4,5-cis-dihydroxy-2-cyclopenten-1-yl)amino)methyl)-7-deazaguanosine).
Synonyms: QTRTD1; FLJ12960
Tractability: Small molecule: a structure with a bound ligand is known. Antibody: UniProt places it where antibodies can reach, with medium confidence. PROTAC: ubiquitination databases record sites on it.
Gene: Protein-coding gene on chromosome 3 (114,005,833 to 114,088,542, forward strand). Ensembl gene ENSG00000151576.
Subcellular location: Cytoplasm; Mitochondrion outer membrane
Subcellular location (Human Protein Atlas): Endoplasmic reticulum; Cytosol; Golgi apparatus; Nucleoli
Pathways (Reactome):
Metabolism of RNA: tRNA modification in the nucleus and cytosol
Gene Ontology:
Molecular function: enzyme-substrate adaptor activity; protein binding; protein heterodimerization activity; protein homodimerization activity; tRNA-guanosine(34) queuine transglycosylase activity
Biological process: tRNA wobble guanine modification; tRNA modification
Cellular component: mitochondrion; transferase complex; tRNA-guanine transglycosylase complex; cytoplasm; mitochondrial outer membrane; cytoplasmic side of mitochondrial outer membrane; protein-containing complex
Genetic constraint (gnomAD): Loss-of-function variants: 22 observed, 34.99 expected, observed/expected ratio (o/e) 0.63, 90% interval 0.45 to 0.9. The upper end of that interval is the gene's LOEUF score, 0.9, which puts it in group 3 of 6, group 1 being the genes least tolerant of losing a copy. Missense variants: 404 observed, 459.34 expected, observed/expected ratio (o/e) 0.88, 90% interval 0.81 to 0.95. Synonymous variants: 163 observed, 178.57 expected, observed/expected ratio (o/e) 0.91, 90% interval 0.8 to 1.04.
Homologues: Orthologues: chimpanzee QTRT2 (99% identical), macaque QTRT2 (95% identical), pig QTRT2 (94% identical), dog QTRT2 (91% identical), guinea pig QTRT2 (89% identical), rabbit QTRT2 (89% identical), rat Qtrt2 (88% identical), mouse Qtrt2 (87% identical), tropical clawed frog qtrt2 (62% identical), zebrafish qtrt2 (55% identical), Drosophila melanogaster CG3434 (29% identical), Caenorhabditis elegans tgt-2 (26% identical). Paralogues in human: QTRT1 (22% identical).
Diseases named in the same sentence as QTRT2 in open-access papers:
QTRT2 is named in the same sentence as 3 diseases in open-access papers, as found by Europe PMC text mining. Sharing a sentence is not in itself a finding about the gene and the disease. The quoted sentences say what the papers report.
glioblastoma (1 paper, 2022). The most malignant astrocytic tumor (WHO grade IV). "For the remaining seven DEPCGs (ZWILCH, RPGR, ZNF460, ZNF528, QTRT2, C5orf15 and CNTRL), no previous functional associations were found with glioblastoma progression, despite a number of them being associated with other cancer types." (PMID 36497269, 2022).
QTRT2 also shares sentences with these, for which no sentence is quoted: cancer (1 paper); glioma (1).